TREM2 (triggering receptor expressed on myeloid cells 2)
Diseases named in the same sentence as TREM2 in open-access papers (continued):
Sharing a sentence is not in itself a finding about the gene and the disease.
atherosclerosis (continued). "However, as atherosclerosis progresses, excessive accumulation and death of foam macrophages regulated by TREM2 may invoke new risk factors for plaque instability and rupture." (PMID 40242752, 2025). "In the context of atherosclerosis, TREM2 signaling promotes foam cell formation and is crucial for maintaining macrophage survival and plaque stability through efferocytosis and cholesterol efflux." (PMID 40083551, 2025). "To further explore the systemic sources and correlates of circulating sTREM2, we assessed its relationship with tissue-level TREM2 expression in paired samples from early-stage lesions (mammary artery), advanced atherosclerosis (aorta), and liver." (PMID 41206594, 2025). "In this review, we summarize the current understanding and the unanswered questions regarding the role of TREM2 signaling in mediating the metabolism and function of macrophages in atherosclerosis and various models of heart failure." (PMID 40083551, 2025). "support the notion that TREM2 in macrophages promotes cholesterol efflux and plays a role in combating atherosclerosis." (PMID 40083551, 2025). "In the periphery, Trem2 also participates in the occurrence and progression of diabetes, liver-related disease, and atherosclerosis by regulating lipid metabolism, inflammation signaling, the viability of immune cells, and apoptosis." (PMID 41460571, 2025). "The expression and role of Trem2 in diseases related to age, such as cancer, diabetes, and atherosclerosis, have been reported recently, with contrasting effects." (PMID 41460571, 2025). "In particular some studies demonstrated that TREM2 is protective for atherosclerosis, while the increase of the presence of some other proteins, like SERPINA3 and C7 led to an increase of cardiac mortality and coronary artery disease respectively." (PMID 40758327, 2025). "Studies using atherosclerosis models have demonstrated TREM2’s diverse roles: myeloid-specific TREM2 deletion reduces oxLDL uptake in foam cells and diminishes plaque progression—even in established lesions—independent of systemic inflammation or lipidemia." (PMID 40940798, 2025). "This review aims to compile existing knowledge and identify gaps regarding the Trem2 signaling pathway in both atherosclerosis and cardiomyopathy, while also considering the potential for therapeutic modulation of TREM2 signaling in cardiovascular disease." (PMID 40083551, 2025). "Galectin-3 acts as a TREM2 upstream factor to regulate macrophage polarization and is also a biomarker of atherosclerosis." (PMID 39497214, 2024). "Phagocytic receptors such as MERTK and TREM2 are thought to have an important role in the resolution of inflammatory processes in atherosclerosis." (PMID 39531316, 2024). "Transcriptomic data showed that in the context of atherosclerosis, Trem2 was predominantly expressed in various macrophage subpopulations, with the highest levels observed in foam cells." (PMID 39497214, 2024). "A more transparent and deeper understanding of the mechanisms by which TREM2 regulates atherosclerosis is essential for the development of appropriate therapeutics." (PMID 39497214, 2024). "In this review, we summarize the latest research developments on TREM2 and its role and mechanisms in atherosclerosis." (PMID 39497214, 2024). "Overall, our data indicate that TREM2 protects from atherosclerosis by limiting necrotic core formation." (PMID 38974464, 2024). "4D9-mediated TREM2 activation primarily improved atherosclerosis in LAB Jak2VF by activating a fibrogenic pathway, possibly mediated by macrophage Pdgfb/fibroblast Pdgfra signaling." (PMID 39531316, 2024).
atherosclerosis (continued). "TREM2 promotes cholesterol uptake and efflux, modulates inflammation and metabolism, and promotes cell survival, making it an attractive target for atherosclerosis research and therapy." (PMID 39497214, 2024). "The dualistic nature of TREM2 in atherosclerosis, where it can exert both protective effect and a side effect of increased lesion size, presents a complex but crucial area of study." (PMID 39497214, 2024). "TREM2 was reported to protect from atherosclerosis by limiting necrotic core formation, which is essential for macrophage efferocytosis." (PMID 39766313, 2024). "These mice were fed a TAM-enriched high-fat diet (TAM-HFD) for 8 weeks to induce atherosclerosis while deleting Trem2 in a macrophage-restricted manner." (PMID 38869957, 2024). "With the aid of single-cell RNA sequencing, macrophages with high expression of TREM2 (TREM2hi) were detected in plaques at different stages of atherosclerosis in mice." (PMID 39497214, 2024). "Since the mechanism of TREM2 in atherosclerosis involves multifaceted biological processes, it has broad applications for the treatment and diagnosis of atherosclerosis." (PMID 39497214, 2024). "Both TREM2 agonistic and blocking antibodies have been developed and utilized for this purpose, which opens up the possibility of TREM2 for the treatment of atherosclerosis." (PMID 39497214, 2024). "In both the setting of obesity and atherosclerosis, these TREM2 macrophage subpopulations function in uptake and disposal of excess lipid." (PMID 39742252, 2024). "Although the relationship between TREM2 and atherosclerosis is still in the early stages of research, some exciting findings have emerged." (PMID 39497214, 2024). "Current research indicates that in the early stages of atherosclerosis, TREM2 promotes lipid uptake by macrophages in response to arterial wall lipid loading." (PMID 39497214, 2024). "Further investigation into the molecular mechanisms is necessary, as a deeper understanding of how TREM2 regulates atherosclerosis is crucial for developing appropriate therapies." (PMID 39497214, 2024). "In the present study, we sought to address the function of TREM2 in atherosclerosis and atherosclerosis-relevant macrophage functions." (PMID 38974464, 2024). "On the other hand, TREM2 influences the progression of atherosclerosis by modulating inflammatory pathways in macrophages." (PMID 39497214, 2024). "In this review, we discuss the roles and mechanisms of TREM2 during different stages of atherosclerotic plaques, as well as the potential applications of TREM2 in the diagnosis and treatment of atherosclerosis." (PMID 39497214, 2024). "Lipid and atherosclerosis pathways were among the top statistically significant altered pathways in both TREM2+ (subcluster 0) and MARCO+ (subcluster 5) macrophages." (PMID 39867899, 2024). "Research on TREM2 as a therapeutic target for atherosclerosis is still in its early stages, yet some agonists previously used in AD models have shown promise for atherosclerosis treatment." (PMID 39497214, 2024). "Although TREM2 is known to play a critical role in inflammation, lipid metabolism, and tissue repair, its role in atherosclerosis is still not fully understood." (PMID 39497214, 2024). "Building on current understanding, we can also draw insights from the role of TREM2 in other diseases to explore its potential impact and therapeutic applications in atherosclerosis." (PMID 39497214, 2024). "While targeting TREM2 holds promise for therapeutic interventions in atherosclerosis, several challenges need to be addressed before its clinical application." (PMID 39497214, 2024). "Overall, these data emphasize the potential for targeting Trem2 to reduce further atherosclerosis progression in patients with established plaques." (PMID 38646596, 2023).
atherosclerosis (continued). "Conditional deletion of Trem2 in foamy macrophages showed attenuated atherosclerosis progression and that targeting Trem2 in established lesions was sufficient to reduce overall plaque burden." (PMID 38646596, 2023). "Aortic arch and aortic sinus were measured for atherosclerotic plaque area and revealed that myeloid-specific deletion of Trem2 in established lesions attenuated further atherosclerosis progression." (PMID 38646596, 2023). "Trem2 regulates macrophage polarization, phagocytosis and survival, but its role in atherosclerosis remains to be examined." (PMID 38646596, 2023). "Like in atherosclerosis, the systemic levels of soluble TREM2 are found to be elevated in humans and mice with NAFLD." (PMID 36994095, 2023). "Together, these data support that Trem2 promotes the formation of foamy macrophages in atherosclerosis." (PMID 38646596, 2023). "Overall, we identify Trem2 as a regulator of foamy macrophage differentiation and atherosclerotic plaque growth and as a putative therapeutic target for atherosclerosis." (PMID 38646596, 2023). "Overall, this study reveals a regulatory module in foamy macrophages reliant on Trem2 for regulating cholesterol accumulation and cell survival and identifies Trem2 as a therapeutic candidate for atherosclerosis." (PMID 38646596, 2023). "In conclusion, additional mechanistic and functional studies are essential to investigate the specific function of TREM2 hi macrophages and explore its therapeutic potential in atherosclerosis." (PMID 35658903, 2022). "In TREM2 hi macrophages, researchers observed increased levels of several types of cathepsins, which can enhance plaque vulnerability and inflammation in atherosclerosis." (PMID 35658903, 2022). "Previous studies showed the increased expression of Trem2 in mouse hearts during atherosclerosis progression and regression." (PMID 35933399, 2022). "Recently, TREM2 has garnered significant attention for its role in atherosclerosis (AS)." (PMID 40242752, 2025). "In atherosclerosis-prone mice, treatment with Trem2 agonism AL002a promote macrophage survival and improves feature of plaque stability.These findings underscore the essential role of TREM2 in maintaining the balance between foam cell death and the clearance of dead cells in atherosclerotic lesions." (PMID 40083551, 2025). "Clinically, TREM2-targeted therapies are hindered by significant challenges, including limited blood–brain barrier penetration and unintended systemic effects (such as increased atherosclerosis)." (PMID 40940798, 2025). "In addition, a recent study demonstrated that hematopoietic or global deficiency of TREM2 increased necrotic core formation in early atherosclerosis, while TREM2 agonism decreased it." (PMID 40083551, 2025). "The identification of soluble TREM2 as a biomarker for differentiating symptomatic from asymptomatic atherosclerosis could significantly enhance early diagnosis and patient stratification in clinical settings." (PMID 41206594, 2025). "It has been observed that TREM2-related research has gradually transitioned from basic studies on cell biology, molecules, and genes to clinical researches on diseases such as central nervous system diseases and atherosclerosis." (PMID 39113887, 2024). "Therapeutic approaches that stabilize MERTK or TREM2 could promote plaque stabilization, especially in CH- and inflammasome-driven atherosclerosis." (PMID 39531316, 2024). "Macrophage Trem2 deletion improves atherosclerosis outcome by limiting foamy macrophage formation." (PMID 38869957, 2024). "Therapeutic approaches that increase MERTK or TREM2 could promote plaque stabilization in inflammasome-driven atherosclerosis." (PMID 39531316, 2024). "Previous evidence indicates that TREM2 functions in other cell types and organs might affect atherosclerosis." (PMID 38974464, 2024).
atherosclerosis (continued). "Additionally, Trem2 drives the differentiation and survival of cholesterol-loaded “foamy” macrophages and the progression of atherosclerosis in CVD." (PMID 38869957, 2024). "Nevertheless, given the possibility that global TREM2 knockout might elevate systemic cholesterol levels, future studies on the role of TREM2 in atherosclerosis require more precise mouse models, such as conditional knockout or bone marrow reconstitution." (PMID 39497214, 2024). "Recent studies have shown that TREM2 promotes macrophage cholesterol uptake and efflux, enhances efferocytosis function, regulates inflammation and metabolism, and promotes cell survival, all of which are significant functions in atherosclerosis." (PMID 39497214, 2024). "The subsequent myeloid-specific deletion of Trem2 attenuated atherosclerosis in vivo." (PMID 38927523, 2024). "Thus, from this perspective, TREM2 in areas other than atherosclerotic plaques, such as adipose tissue, can affect atherosclerosis by influencing systemic lipid levels." (PMID 39497214, 2024). "Some studies suggested that TREM2 may play a role in regulating homeostasis of dendritic cells and their response to pathogens, though its function in the setting of atherosclerosis remains unclear." (PMID 39497214, 2024). "Additionally, since sTREM2 serves as a marker or has therapeutic benefits in many diseases, its function in atherosclerosis and its relationship with TREM2 should be investigated." (PMID 39497214, 2024). "More research is needed to determine whether TREM2 functions similarly in atherosclerosis, which can help identify pathological mechanisms and therapeutic strategies for this disease." (PMID 39497214, 2024). "In atherosclerosis Trem2+ LAM macrophages had been identified in mouse and human arteries." (PMID 37781401, 2023). "Together, these data show that Trem2 is required for atherosclerosis progression and support the hypothesis that Trem2 regulates foamy macrophage formation in atherosclerotic lesions." (PMID 38646596, 2023). "Because humans are diagnosed with atherosclerosis once plaque has already developed, we wanted to test whether Trem2 can be targeted therapeutically in established atherosclerotic lesions." (PMID 38646596, 2023). "In cardiovascular disease, recent studies support the role of Trem2 in atherosclerosis." (PMID 36982629, 2023). "Importantly in relation to atherosclerosis, genes related to lipid metabolism, which featured in resident macrophages, were downregulated (Plin2, Trem2, Lipa, Msr1, and Abcg1) by CLEC4A2 deletion." (PMID 35017526, 2022). "Consequently, adrenal gland macrophages regulate adrenocortical steroidogenesis in acute and chronic stress conditions, like cold exposure and atherosclerosis, respectively, through a mechanism dependent on TREM2 and macrophage-specific TREM2 deletion in mice increases serum glucocorticoid levels." (PMID 40551885, 2025). "TREM2 may affect atherosclerosis by regulating macrophage lipid absorption and processing." (PMID 39497214, 2024). "In addition, the use of Apoe−/− mice may interfere with studies on TREM2, as APOE is a known downstream effector of TREM2.Here, we summarize the mouse models used in current atherosclerosis research and their respective findings for reference." (PMID 39497214, 2024). "However, the role of TREM2-expressing neutrophils in atherosclerosis has yet to be investigated." (PMID 39497214, 2024). "However, the role of TREM2 in atherosclerosis is not fully known." (PMID 38974464, 2024). "Moreover, typical applications of TREM2 in other diseases may offer valuable insights for its therapeutic use in atherosclerosis." (PMID 39497214, 2024).
atherosclerosis (continued). "However, whether TREM2 affects systemic lipid levels in the context of atherosclerosis remains to be investigated." (PMID 39497214, 2024). "To determine if activation of TREM2 could improve atherosclerosis in LAB Jak2VF CH mice, we administered 4D9 or isotype control IgG antibodies by i.p. injection beginning 2 weeks after initiation of the WD and continued the injections and the diet for an additional 14 weeks." (PMID 39531316, 2024). "Interestingly, Trem2+ LAMs expressing Spp1 showed a transcriptional profile similar to osteoclasts during advanced stages of murine atherosclerosis, and human multinucleated giant cells express MAM markers such as SPP1, MMP9, CHI3L1 in granulomatous slack skin." (PMID 37706477, 2023). "Therefore, TREM2 is speculated to exacerbate atherosclerosis development." (PMID 40083551, 2025). "The direct impact of TREM2 deficiency may involve a reduction in the expression of cholesterol transporters, such as ABCA1 and ABCG1, that impairs cholesterol efflux, compromises cell survival, which seems to exacerbate the pathological process of atherosclerosis." (PMID 40242752, 2025). "In atherosclerosis, TRM as well as MDMs can acquire a foamy phenotype characterized by the expression of TREM2." (PMID 40384967, 2025). "The goals of the present study were to assess atherogenesis in a hyperlipidemic, LAB model of Jak2VF, then to define the mechanisms of accelerated atherosclerosis, especially those involving IL-1β–mediated crosstalk from mutant to WT myeloid cells that led to reduced levels of MERTK and TREM2." (PMID 39531316, 2024). "Therefore, Trem2+ LAM macrophages are essential for the maintenance of adipose tissue homeostasis and control of metabolic diseases including atherosclerosis." (PMID 37781401, 2023). "Functional studies assessing the role of TREM2 in NAFLD and atherosclerosis are still required since this receptor might also be involved in a common lipid-induced mechanistic pathway." (PMID 35083304, 2021). "In addition, TREM2-dependent Abca1 and Abcg1 expression and cholesterol efflux have been reported to explain the sexually dimorphic effect of serum amyloid A3 (SAA3) on atherosclerosis." (PMID 40083551, 2025). "Related studies have also indicated that TREM2 accelerates the transformation of vascular smooth muscle cells and macrophages into foam cells by upregulating the expression of the scavenger receptor CD36, thus enlarging plaque volume and exacerbating the progression of atherosclerosis." (PMID 40242752, 2025). "Although this has not been confirmed in the context of atherosclerosis, the high expression of TREM2 on foam cells is hypothesized to be an adaptive response to cholesterol load, through which normal lysosomal cholesterol processing is maintained to prevent toxic cholesterol accumulation." (PMID 40083551, 2025). "Single-cell RNA sequencing uncovered that the lack of LXR altered the expression of expected TREM2 target genes: there was a marked switch to a pro-inflammatory phenotype, with reduction of cholesterol-handling and efflux proteins, promoting increased atherosclerosis." (PMID 39742252, 2024). "Moreover, to determine the translational impact of the TREM2/TREM1, and Olfr2 therapies, the development of induced pluripotent stem cells derived in-vitro vascular organoids may be beneficial to screen drugs that are more effective in lowering atherosclerosis disease burden in humans." (PMID 40384967, 2025).